CD28 (CD28 molecule)
Diseases named in the same sentence as CD28 in open-access papers (continued):
Sharing a sentence is not in itself a finding about the gene and the disease.
tumor (continued). "Engineering with a CD3ζ or CD28-CD3ζ signalling CAR may overcome some, but not all defects in “burn-out” T cells of progressed tumor patients." (PMID 21837241, 2012). "To assess whether IL-2 signaling is required for IL12R upregulation on tumor-reactive T cells in the TdLN, we primed naive cell trace violet–labeled (CTV-labeled) CD8+ T cells with plate-bound CD3 and CD28 agonist antibodies in the presence or absence of neutralizing IL-2 antibodies." (PMID 37669107, 2023). "The CD8+ T lymphocytes can be further divided into CD8+CD28+ T lymphocytes (CTL) and CD8+CD28− T lymphocytes based on the expression of CD28 on the surface of CD8+ T lymphocytes, of which CD8+CD28− T lymphocytes are a class of regulatory T cells that do not have tumor-killing functions." (PMID 37206348, 2023). "For instance, it is reported that 4-1BB signaling in CD19 CAR T cells, unlike CD28, produces positive feedback on the gammaretroviral long terminal repeat (LTR) promoter through NF-κB activation, resulting in CAR T cell apoptosis and inefficient anti-tumor performance." (PMID 36139135, 2022). "In addition, we could not prove the predictability of tumor-suppressive subtypes of peripheral CD8+ T cells (CD107a+, CD28+), while other studies demonstrated that a high frequency of CD8+ or CD8+CD28+ T cells predicted better prognosis." (PMID 36333670, 2022). "To investigate if these ligands may reduce activation in exhausted tumor-infiltrating MAIT cells, and thus if MAIT cells might respond to checkpoint blockade therapy, we stimulated MAIT cells with anti-CD3 and anti-CD28 antibodies in the presence or absence of neutralizing antibodies to PD-1." (PMID 33885944, 2021). "Using CD3+/CD28+ T cells isolated from immune competent mice, we observed that NextA did not induce major changes in the production of either IFNγ and IL2, implying that the anti-tumor activity of HDAC6i was not mediated by the direct action of this drug on T cells." (PMID 30992475, 2019). "Contrasting against the high expression of CD28 in RPCI-WM1 cells, this finding was not wholly unexpected as RPCI-WM1 cells were established from a highly drug refractory and terminal WM patient, whereas, the primary tumor cells tested herein are from patients with a less aggressive disease course." (PMID 25853860, 2015).
cancer (332 papers, 2004 to 2026). A tumor composed of atypical neoplastic, often pleomorphic cells that invade other tissues. "Overexpression of CTLA-4 can competitively inhibit the CD28 co-stimulatory signal required for optimal T cell activation, leading to a loss of anti-cancer activity." (PMID 39995821, 2024). "In contrast, the limited fratricide associated with CD5 2G (CD28) CAR-T-cells allowed for sufficient cellular expansion to exert antitumor activity toward T-cell malignancies." (PMID 37626869, 2023). "These include CD8+CD28- cells which have been associated with different clinical conditions such as pregnancy, infectious diseases, cancer, and organ transplantation." (PMID 38259469, 2023). "CD276 (also known as B7-H3) is one of the most important immune checkpoints of the CD28 and B7 superfamily, and its abnormal expression is closely associated with various types of cancer." (PMID 36717836, 2023). "The P13K-AKT pathway is associated with the CD-28 co-stimulatory receptor and cytokine receptor in almost all cancer cells including TCL, and this pathway is activated in an inappropriate way." (PMID 37746258, 2023). "PD-1 engagement by PD-L1 on cancer cells is known to interfere with TCR/CD28-dependent T cell signaling by blocking exhaustion-associated transcription factors, including the AP-1, NF-κB, and NFAT." (PMID 34054817, 2021). "The relationship between the CD28 rs3116496 polymorphisms and susceptibility to various diseases, including cancer, has been previously investigated." (PMID 23133541, 2012). "Cytotoxic T-lymphocyte-associated antigen 4 (CTLA-4), which competes with CD28 for B7 binding, has been widely accepted as a new promising target for cancer immunotherapy." (PMID 23133541, 2012). "However, while polymorphisms in the CD28 co-signaling molecule have been shown to contribute to cancer initiation and progression, significant work remains to fully develop its potential as both a screening/diagnostic tool and a therapeutic marker." (PMID 40143377, 2025). "Moreover, CD28-mediated T cell co-stimulation has been shown to be crucial for PD-1 therapy in cancer patients as loss of CD28 via T cell exhaustion was shown to correlate to clinical irresponsiveness towards PD-1 ICI." (PMID 38440738, 2024). "Likewise, a bispecific aptamer (MRP1-CD28) was used to guide CD28 agonistic aptamers to cancer stem cells expressing multidrug resistance-associated protein 1 (MRP1, also called ABCC1), which is ubiquitously expressed in aggressive tumors." (PMID 35189921, 2022). "As for co-stimulators, GMFG was highly associated with CD80 and CD28 in most cancers." (PMID 33863293, 2021). "In cancer, CTLA-4 expression is induced in T cells after TCR activation and its signaling starts when APCs migrate from cancer to draining lymph nodes, here presenting the tumour-associated antigen to T lymphocytes, replacing CD28 by the interaction with B7 ligands." (PMID 33383673, 2020). "It is now well known that cancer could accelerate differentiation of T cells into a senescent state, and their treatments such as DNA-damaging chemotherapy could lead to premature aging of T cells with CD28 loss." (PMID 37939189, 2023). "It has been shown that the number of genetic mutations in patients, the presence of CMTM6 molecules, CD28/B7 status, and intestinal microbes may be associated with new antigens on the surface of cancer cells, PD-L1 half-life, T cell activity, and T cell recruitment, respectively." (PMID 31182061, 2019). "Therefore, CD28 gene mutations may break the balance between costimulatory and coinhibitory molecules and changed the susceptibility of cancer." (PMID 29089469, 2017). "In vivo administration of LPC-LNP-Cd28 successfully knocked down 80% of cancer cell CD28, substantially reduced PD-L1 expression, and circumvented the off-target immunosuppression observed with commercial lipid formulations." (PMID 42261788, 2026).
cancer (continued). "The increase in PD-1 levels observed in the current study correlates with a decrease in CD28 in the HIV singly infected group, which potentially contributes to immunosuppression and susceptibility to cancer initiation." (PMID 40143377, 2025). "CTLA-4 is an inhibitory molecule that competes with the co-stimulatory molecule CD28 for binding, thereby regulating T-cell responses against pathogens and cancer." (PMID 40143377, 2025). "The helminth-induced upregulation of immune checkpoints and reduction of costimulatory molecules, such as CD28, share similarities in immune modulation observed in cancer with a potential significant impact on cancer immunotherapy." (PMID 40143377, 2025). "The observed improvements in cytotoxicity, reduced exhaustion, and enhanced in vivo persistence of NKG2D/CD28&CAR-T cells highlight their potential as a valuable approach in cancer immunotherapy." (PMID 40181405, 2025). "This suggests that PD-1 therapy induces the selective proliferation of CD8+ T cells, highlighting the potential of CD28 as a biomarker for predicting CD8+ T cell responses in cancer patients." (PMID 40385461, 2025). "Conversely when CD28 binds to B7-1 or B7-2 on the surface of cancer cells, T-cell killing is enhanced." (PMID 39682188, 2024). "The activation process is achieved by more than one method that work on the stimulation of CD3 and CD28, and the most popular method is using paramagnetic beads coated with anti-CD3 and anti-CD28 imitating a cancer cell with these surface antigens." (PMID 39312080, 2024). "CAR T cells containing CD28 have been shown to enhance anti-cancer functions and persistence both in vitro and in vivo." (PMID 38683232, 2024). "CD28 (also known as Tp44), discovered in 1986, is the first co-stimulatory molecule for cancer immunotherapy." (PMID 38257366, 2024). "Blocking CTLA-4 is capable of generating an immune response to cancer and self-tissue, and targeting the CD28/CTLA-4 pathway with antibodies has shown considerable promise in the treatment of cancer and autoimmune diseases." (PMID 39845973, 2024). "We discovered that in the lymphocyte-depleted cancer model, CD28 costimulation enabled by ICB drove the RT-induced Treg response." (PMID 38349740, 2024). "Coexpression of CD80 and PD-L1 on cDCs positively correlated with enhanced CTL priming capacity against cancer, in agreement with increased formation of a CD28-costimulatory CD80:PD-L1 heterodimer." (PMID 38349740, 2024). "Nevertheless, we observed expression of CD27, CD28 and CD62L on many TAII cells, which have been associated with clinical responses and high anti-cancer activity and persistence." (PMID 38184565, 2024). "We observed lower levels of CD4+T, memory CD4+T, and CD4+CD28+T cells in distant metastatic UGI cancers than in locally advanced cancers." (PMID 37346066, 2023). "Next, we focused on the role of co-stimulatory molecules other than CD28, i.e. ICOS, CD137 (4-1BB), and integrin CD11a as contributors to the functional fitness of PD1+CD28− T cells in peripheral blood of NSCLC cancer patients." (PMID 37898752, 2023). "The activated T-cell metabolism resembles cancer cell metabolism up on activation through T-cell receptor signaling accompanied by co-stimulation through CD28 induction." (PMID 37746258, 2023). "Following this, we also observed increased Tcm–Tscm ratios and anti-cancer activity of CAR-T cells activated with PHA compared with anti-CD3/anti-CD28-activated CAR-T cells." (PMID 36851194, 2023). "Proper activation of cytotoxic T cells via the T cell receptor and the costimulatory receptor CD28 is essential for adaptive immunity against viruses, intracellular bacteria, and cancers." (PMID 38127070, 2023). "To target upregulated ErbB dimer expression in this cancer, we developed an autologous CD28-based chimeric antigen receptor T-cell (CAR-T) approach named T4 immunotherapy." (PMID 37321663, 2023).
cancer (continued). "Proper activation of cytotoxic T cells via the T cell receptor and the costimulatory receptor CD28 is essential for adaptive immunity against viruses, many intracellular bacteria and cancers." (PMID 37547023, 2023). "CTLA-4 receptor is a decoy competitor of the cluster of differentiation 28 receptor (CD28), highly expressed on T-Cell effectors for B7-1 and B7-2 ligands of cancer cells." (PMID 37185406, 2023). "This study showed that the ratios of PD-L1 or PD-L2, normalized with ICOS and other CD28 members, also allowed for a good survival prediction for all cancers and HNSCC with nodal involvement in both cohorts using univariate modes." (PMID 36983005, 2023). "Requirement for CD28 co-signalling is the reason for the inclusion of the intracellular domain of CD28 in the design of some chimeric antigen receptors in cancer therapies." (PMID 35050850, 2022). "The connection between PD-1 and its ligand, PD-L1, expressed on the cancer cell surface, barriers TCR signaling and CD28 co-stimulation and ultimately causes down-regulated T cell activity and ensuing tumor evasion." (PMID 36510217, 2022). "As previously reported, in the cancer-immunity cycle, CD28: (CD80, CD86), CD40, CD27, HVEM, GITR: GITRL, ICOS, and TLR-2 are stimulatory factors, while TIM-3, PD-L1: PD-1, PD-L1: (CD80, CD86), CTLA-4: (CD80, CD86), BTLA, and LAG-3 are inhibitory factors." (PMID 35419462, 2022). "In keeping with these findings, CD28 agonists have been developed that awaken T cells from a tolerant state and activate the immune system in the treatment of cancer and infection." (PMID 36618349, 2022). "In another study, a second-generation CAR containing EGFRvIII-specific antibody MR1-1 as cancer-targeting domain and CD28 and CD3ζ as signaling domains was used for transduction into the NK cell." (PMID 33752707, 2021). "Its role in modulation of adaptive immune responses, for example suppressing T cell-mediated immune responses, was originally identified in a murine model of cancer that Gr-1+ cells can inhibit T cell activation through CD3/CD28 co-stimulation." (PMID 34557202, 2021). "In some preclinical studies, NK-92 cells were transduced with second-generation CARs containing a composite CD28-CD3ζ signaling domain to target ErbB2-positive cancer cells." (PMID 33752707, 2021). "In our study, HCG18 was the only one lncRNA potentially competing with CD28, which had been reported to be relevant to immune cell infiltration in cancer." (PMID 34794447, 2021). "Among all the significant associations, CD36 expression was positively correlated with CD27, CD28, CD40, and ICOS in multiple cancer types, but negatively associated with CD40 in TGCA." (PMID 34234847, 2021). "It belongs to the CD28 supergene family and plays a critical role in the regulation of immunological tolerance, and in immune cell responses against pathogens and cancer." (PMID 35693319, 2021). "This study uncovers a previously unidentified role for CD28 costimulation in CD8+ T cell activation and suggests that the CD28 costimulatory pathway can be a potential target for cancer immunotherapy." (PMID 34011962, 2021). "Remarkably, miR‐21 has been characterised also for its anti‐apoptotic function in cancer cells, and CD28 costimulation supports T‐cell activation also by delivering anti‐apoptotic signals, mediated in large part by the PI3K pathway member Akt." (PMID 34584693, 2021). "Lastly, the identification of the targets of p56lck in the TCR and CD28 provided the framework for the development of chimeric antigen receptor (CAR) therapy in the treatment of cancer." (PMID 33791292, 2021). "The role of transduction signaling protein EP300 mutated in cancer has been evidenced that it activated miRNA MIR17 to negatively regulate target genes BECN1 and CD28 to promote cell proliferation and escape the immune checkpoint." (PMID 33802957, 2021).
cancer (continued). "Within this frame, recent advances in engineering bispecific antibodies targeting CD28 costimulatory molecule should also be considered for optimizing cancer-specific immunotherapy." (PMID 33138029, 2020). "The mechanism by which CD28 affects carcinogenesis and cancer development in LUAD needs further study." (PMID 32967633, 2020). "For example, type 1 diabetes was related to both the CD28 gene and the CTLA-4 gene, as well as rheumatoid arthritis and cancer risk in Asians." (PMID 32210155, 2020). "T cells from healthy volunteers were stimulated with anti CD3/CD28 micro beads and cultured in presence of CM from cancer cells lines." (PMID 33123122, 2020). "For this purpose, fresh TILs obtained from a number of surgical specimens of a variety of cancers were stimulated with anti-CD3/CD28 mAbs in combination with TNF blocking agents." (PMID 32292509, 2020). "In fact, the success of PD-1 immunotherapy in chronic infection and cancer is dependent on CD28 signaling." (PMID 33613516, 2020). "The concept that CD28 is involved in the proliferation of memory T cells is intriguing in the light of recent data related to checkpoint blockade for cancer treatment." (PMID 33223527, 2020). "Since CD8+CD28− cells are derived from the general population of immature CD8+CD28+ T cells originating from the thymus, the production of immature CD8+CD28+ decreases as thymic involution occurs through aging, but also with cancer." (PMID 31181772, 2019). "CD8+CD28− cells represent a distinct population distinguishable from the general population of CD8+CD28+ T cells, which are known for their crucial role in the clearance of cancer and intracellularly infected cells, in terms of their phenotype and function." (PMID 31181772, 2019). "Among the many facets of CD8+ T cell dysfunction, including tolerance, anergy, and exhaustion, CD8+ T cell senescence, as represented by the CD8+CD28− population, is an emerging field and their presence has been described in many cancers." (PMID 31181772, 2019). "The superfamily member B7/CD28 has been shown to play an important role in the immune response, and they are seen as effective markers in cancer diagnosis and treatment." (PMID 31792298, 2019). "PD-1 is a member of the CD28/B7 family and acts as an immune checkpoint in various malignant tumors." (PMID 31192256, 2019). "The PD-1/PD-L1 immune checkpoint blockage in cancer therapy, the interfering CD28 and CD80/CD86 binding with CTLA-4-Ig in the treatment of rheumatoid arthritis and using anti-CTLA-4 monoclonal antibody (mAb) for cancer treatment are the best examples." (PMID 31120992, 2019). "Current evidence shows that the downregulation of CD28 is a hallmark of senescent CD8+ T cells and CD28− senescent T cells display immunosuppressive functions in cancer." (PMID 31181772, 2019). "In co-stimulators, we demonstrated that the CD80 and CD28 expression was highly correlated with PD-1 in some of cancer types." (PMID 30607140, 2018). "The broad expression of CD58, CD112 and CD155 on cancer cells provided a rationale to assess CD2::CD28 and CD226::CD28 chimeras." (PMID 29707134, 2018). "As cancer-targeting therapeutic agents, aptamers can be agonists that activate the function of targets related to cancer suppression or immunity, such as CD28, CD134, and CD137." (PMID 29617327, 2018). "Multiple circRNAs have been suggested as potential biomarkers of specific cancer diseases and CD28-related CD8(+) T-cell ageing." (PMID 29523209, 2018). "To prepare the diabody-type bispecific antibody library, we used 4 anti-T-lymphocyte Fvs with affinity for CD3 or CD28, and 13 anti-cancer Fvs with affinity for members of the EGFR family (EGFR, HER2–4) 18, 22–39." (PMID 28588218, 2017). "CD28 co-stimulatory function is also relevant for cancer immunotherapy, as chimeric antigen receptors (CARs) containing CD28 cytoplasmic regions have been shown to induce efficient T cell effector functions." (PMID 26870040, 2016).